IL18 (interleukin 18)
Diseases named in the same sentence as IL18 in open-access papers (continued):
Sharing a sentence is not in itself a finding about the gene and the disease.
celiac disease (8 papers, 2010 to 2026). An autoimmune genetic disorder with an unknown pattern of inheritance that primarily affects the digestive tract. "Our results suggest a possible haplotypic association between SNPs in the IL18 locus and coeliac disease risk." (PMID 20478055, 2010). "A recent study, which included analysis of the Irish samples analysed in this study, has identified functional genetic variants at IL18RAP, a receptor for IL18, as a risk factor in coeliac disease." (PMID 20478055, 2010). "An increased level of interleukin-17A and interleukin-18 in the serum and intestinal mucosa of celiac disease patients reflecting the severity of villous atrophy and inflammation was documented." (PMID 38756445, 2024). "Previous studies have shown that IL-17A and IL-18 are elevated in the serum and intestinal mucosa of celiac disease patients, and correlate with the severity of villous atrophy and inflammation." (PMID 38756445, 2024). "This reduced IL-18 cytokine expression in celiac disease is consistent with the overall reduced expression of SLC9A4 observed among diabetic neutrophils in our study." (PMID 34134627, 2021). "Dual activation of IRF1 and IRF1-regulated genes, both directly and via the interleukin-18 dependent inflammasome would drastically enhance the inflammatory response and lead to the pathological situation seen in active celiac disease." (PMID 28934294, 2017). "IL18R1 is part of the cytokine receptor cluster on chromosome 2q12 which encodes for the receptors of IL18; a cytokine involved in IFN-gamma synthesis and its mRNA expression is upregulated in active patients with celiac disease." (PMID 27015091, 2016). "Interestingly, tissue explants from patients with active celiac disease show IL-18 expression only in the crypts." (PMID 30319613, 2018). "The IL-18 pathway induces synthesis of the cytokine IFN- γ in T cells, which has been shown to act in mucosal inflammation in celiac disease." (PMID 34134627, 2021). "IL-18 has been shown to be elevated in autoimmune colitis including IBD and celiac disease and is a key mediator of intestinal homeostasis." (PMID 30319613, 2018). "In this study, the salivary levels of interleukin-17A, interleukin-1beta, and interleukin-18 in 23 celiac disease patients on a gluten-free diet were evaluated against 23 non-celiac controls." (PMID 38756445, 2024). "Upon barrier compromise as seen in celiac disease and IBD, CCL20 and IL-18 might be able to drive immune cell migration to the lamina propria which might explain the reported beneficial effect of an gluten-free diet and increased serum CCL20 and IL-18 levels in celiac patients." (PMID 41585485, 2026). "In addition, tests for epistasis using Plink software did not suggest any interaction between these IL18 and IL18RAP genes in coeliac disease susceptibility." (PMID 20478055, 2010).
Cryptosporidium infection (8 papers, 2020 to 2025). "In particular, intrinsic activation of caspase-1 in epithelial cells has been shown to positively influence interleukin-18 (IL-18) secretion, which is important for activating immune reactions during cryptosporidiosis." (PMID 40005845, 2025). "We recently reported that an enterocyte intrinsic NLRP6 inflammasome is activated by Cryptosporidium infection leading to release of IL-18." (PMID 35584177, 2022). "IL-18 is an important immune mediator in cryptosporidiosis and decreased levels of this cytokine result in increased susceptibility and infection levels." (PMID 32532051, 2020). "Different studies using transgenic mice have shown that deficiencies in either Th1 cytokines, such as IL-12, IL-18, and IFN-γ, or inflammasome components (caspase-1) are associated with a more susceptible or sometimes lethal phenotype to Cryptosporidium infection." (PMID 36211380, 2022). "Significant gaps remain in our understanding of the cellular source of IL-18 during Cryptosporidium infection and its ability to promote innate production of IFNγ and whether it is required for tissue repair independent of IFNγ." (PMID 33372132, 2021). "IL-18, a product of the inflammasome complex, is elevated in human epithelial cell lines following C. parvum infection; moreover, IL-18 knockout and inflammasome components caspase-1 or ASC knockout mice are more susceptible to Cryptosporidium infection than control mice." (PMID 34113580, 2021). "Taken together, these data support a model of innate recognition of Cryptosporidium infection through an NLRP6-dependent and enterocyte-intrinsic inflammasome that leads to the release of IL-18 required for parasite control." (PMID 33372132, 2021). "Finally, we tested the level of secretion of interleukins IL-1β and IL-18, which are involved in the NLRP6 inflammasome, recently described as a key mechanism for enterocyte’s defense against Cryptosporidium infection in a mouse model." (PMID 38189373, 2024). "We found the production of IL-18, an enterocyte derived cytokine induced by Cryptosporidium infection, to be intact in the absence of TLR3 (Standard t-test *** p <0.001)." (PMID 35584177, 2022).
diabetic retinopathy (8 papers, 2017 to 2024). "The results of the current study also suggest that MGCs can play an important role in regulating the expression of pro-inflammatory cytokines such as IL-1β, ΙL-6, TNF-α, and IL-18 in the early stages of diabetic retinopathy, which was proposed to be associated with the inflammasome activation." (PMID 34071438, 2021). "By inhibiting the activation of NLRP3, ASC, caspase-1, and NF-κB to reduce the production of IL-1β and IL-18, propelling RvD1 to be expected an effective means to alleviate the progression of diabetic retinopathy." (PMID 33967796, 2021). "Studies in diabetic retinopathy indicate that Cx43 hemichannels lie upstream of inflammasome activity, with aberrant ATP release activating the P2 × 7 receptor, NLRP3 assembly and resultant caspase 1-mediated cleavage of IL1ß and IL18." (PMID 38970061, 2024). "A previous study also demonstrated the correlation between IL-18 and VEGF in patient with diabetic retinopathy, suggesting that IL-18 may contribute to retinal angiogenesis by acting together with VEGF27." (PMID 28785068, 2017).
Hyperinsulinemia (8 papers, 2013 to 2024). An increased concentration of insulin in the blood. "In response to acute hyperinsulinemia, a decrease of TNFα, IL-8, and IL-18 circulating levels was observed in healthy lean subjects, while in first-degree relatives (FDR) of type 2 diabetic patients, this anti-inflammatory response was blunted." (PMID 30983877, 2019). "Compared to a reference bottlenose dolphin without metabolic perturbations, the current study identified activated cytokine gene expression, including TGF-β, TNF-α, IFN-γ, IL-18, IL-13, IL-10, and IL-4 in the liver or spleen of a geriatric bottlenose dolphin with hyperinsulinemia." (PMID 24101915, 2013). "Consistent with the findings in the mouse, hyperinsulinemia increased the mRNA levels of both p21 as well as SASP factors IL8, IL18, and IL32 in IHH cells, demonstrating the pro-senescent effect of prolonged hyperinsulinemia also occurs in human liver cells." (PMID 35872305, 2022).
mastocytosis (8 papers, 2014 to 2024). A clonal myeloproliferative neoplasm characterized by the proliferation and accumulation of neoplastic mast cells in one or multiple organs or organ systems. "IL-18 induces mastocytosis by increasing the mast cell growth factor IL-3, thereby promoting the elimination of S. venezuelensis." (PMID 30717382, 2019). "C57BL/6 mice pretreated with IL-18 and IL-2 developed mucosal mastocytosis and had high levels of serum mMCP1 (mouse mast cell protease 1), an activation marker of mucosal mast cells." (PMID 30717382, 2019). "Because IL-3 and IL-9 induce mucosal mastocytosis, we examined the capacity of mice injected with IL-2 and IL-18 to protect against infection with S. venezuelensis." (PMID 30717382, 2019). "We found that C57BL/6 mice pretreated with IL-18 and IL-2 developed mucosal mastocytosis with high levels of serum mMCP1, an activation marker of MMC, and became able to promptly expel the intestinal nematode Strongyloides venezuelensis." (PMID 29731751, 2018). "We previously reported that administration of IL-18 induces intestinal mastocytosis and such IL-18-pretreated mice gain the capacity to strongly expel implanted adult worms." (PMID 24678315, 2014). "It is known that IL-18 activates MCs and can lead to the formation of mucosal mastocytosis." (PMID 38539560, 2024). "Thus, IL-18 is important for expulsion of intestinal nematodes by induction of mucosal mastocytosis, and we published these results in J Exp Med." (PMID 29731751, 2018). "Because IL-3 and IL-9 induce mucosal mastocytosis, we examined whether the animals developed mucosal mastocytosis after treatment with IL-2 and IL-18." (PMID 29731751, 2018). "The report that IL-18-dependent mastocytosis and mast cell activation are important for prompt parasite expulsion may also support the current finding." (PMID 27069315, 2016).
migraine (8 papers, 2017 to 2025). "Along with IL-6, pro-inflammatory cytokine IL-18 is also up-regulated in serum of all migraine patients, albeit stronger in patients with the gene mutation." (PMID 28900389, 2017). "Inhibition of PD-1 amplified migraine-induced hyperalgesia was accompanied by increased calcitonin gene-related peptide, interleukin-1β, tumor necrosis factor α, interleukin-6, and interleukin-18 in the trigeminal ganglia of mice." (PMID 40002809, 2025). "The level of IL-18 in blood of migraine patients was significantly higher than that of control group." (PMID 39416954, 2024). "Recent studies investigating neuroinflammation in migraine reveal the role of inflammasome via inflammasome complex players including IL-1β and IL-18." (PMID 35896985, 2022). "IL-18-mediated microglia/astrocyte interactions in the medullary dorsal horn likely contribute to the development of hyperpathia or allodynia induced by migraines." (PMID 35987639, 2022). "Neuroinflammation pathways, specifically those involving inflammasome proteins, such as IL-1β, IL-18, and caspase-1, seem promising candidates as biomarkers or treatment targets in migraine, providing some interesting direction for further study." (PMID 35896985, 2022). "First, we found that serum levels of classical pro-inflammatory IL-6 and IL-18 were higher in all patients with migraine, irrespective of the presence of the mutation." (PMID 28900389, 2017).
neuroblastoma (8 papers, 2012 to 2024). Neuroblastoma (NB) is the most common solid, extracranial childhood tumor. "IL-23-producing CAR T cells are particularly promising, able to regress neuroblastomas to a greater extent than IL-15- or IL-18-secreting CAR T cells." (PMID 39199630, 2024). "A previous study with human neuroblastoma cells identified induction of IL-18 by all trans retinoic acid in vitro." (PMID 32330185, 2020). "The cytokines IFN-γ, IL-2, IL-7, IL-12, IL-15, IL-18, IL-21, and IL-27, promoted neuroblastoma regression via enhancing the efficacy of effector cells, whereas VEGF, IL-6, and IL-10 induced neuroblastoma progression through their immunosuppressive activities." (PMID 33322408, 2020). "First we examined the presence of IL-18 receptor (IL-18R) and IL-18 bp in differentiated SH-SY5Y neuroblastoma cells." (PMID 22898493, 2012). "We differentiated SH-SY5Y neuroblastoma cells as neuron-like and exposed them to IL-18 for various times." (PMID 22898493, 2012). "The effect of IL-18 on human neuroblastoma cells (SH-SY5Y) has previously been reported, in which IL-18 significantly upregulated the expression of several AD-related genes such as PS1 and BACE1." (PMID 32033164, 2020). "In this study, we examined the relationship of IL-18 on APP processing and Aβ formation in vitro in neuron-like differentiated SH-SY5Y-neuroblastoma cells." (PMID 22898493, 2012). "We examined how IL-18 affects protein levels of particularly BACE-1 and PS-1 in neuron-like differentiated SH-SY5Y neuroblastoma." (PMID 22898493, 2012). "Simultaneously created four oncolytic HSV-1 vectors, which express murine soluble B7.1 (vHsv-B7.1-Ig), murine IL-12 (vHsv-IL-12), murine IL-18 (vHsv-IL-18), and no transgene, were tested in A/J mice harbouring s.c. tumours of syngeneic and poorly immunogenic Neuro2a neuroblastoma." (PMID 36140243, 2022).
neuropathy (8 papers, 2015 to 2026). A disorder affecting the nervous system that manifests with pain, tingling, numbness, and/or muscle weakness. "Interleukins (IL-1beta, IL-18 and IL-6) are recognized as the first pronociceptive cytokines in neuropathy and are known to be strongly activated upon neural damage in the CNS and PNS." (PMID 32691345, 2020). "LPS-RSU restored the balance between algesic IL-18 and analgesic IL-18BP, additionally increasing the IL-6 level, which in neuropathy is known to have analgesic properties." (PMID 29656686, 2018). "The nociceptive factors that undergo the strongest activation during neuropathy include iNOS, IL-1beta, IL-18 and IL-6." (PMID 26426693, 2015). "In addition, in subjects with neuropathy, an increase in the spinal expression of IL-18 occurs that is parallel to the appearance of symptoms of neuropathic pain and the activation of microglial cells." (PMID 34681732, 2021). "Moreover, a highly specific TLR4 antagonist modulated the interleukin expression levels in DRG, restoring the balance between pronociceptive IL-18 and analgesic IL-18BP, and increased the IL-6 level, which in neuropathy is known to have analgesic properties." (PMID 29656686, 2018). "Our previously published results showed that inhibition of NF-κB by its potent inhibitor, parthenolide, diminished symptoms of neuropathy, potentiated morphine analgesia, and diminished pronociceptive markers of microglial cell polarization (IL-1β, IL-18, and iNOS)." (PMID 28573049, 2017). "We have shown that the inhibition of NF-κB with a potent inhibitor, parthenolide, not only diminished the symptoms of neuropathy but also potentiated morphine analgesia and reduced the levels of pro-inflammatory factors produced by microglia (IL-1β, IL-18, NOS2)." (PMID 28491822, 2017). "Our previously study demonstrated that minocycline diminished the level of proinflammatory factors, such as IL-6, IL-18, and MMP-9, during neuropathy and enhanced morphine effectiveness." (PMID 26426693, 2015).
osteosarcoma (8 papers, 2017 to 2025). A usually aggressive malignant bone-forming mesenchymal neoplasm, predominantly affecting adolescents and young adults. "Here the authors show that doxorubicin promotes IL-18 secretion by tumor associated macrophages inducing LAT2-dependent CD47 upregulation in osteosarcoma cells, suggesting LAT2 inhibition as a therapeutic option in combination with doxorubicin." (PMID 36274066, 2022). "Another study showed the relationship between the levels of myeloid-derived suppressor cells (MDSCs) and IL-18 expression in osteosarcoma tumor models." (PMID 40115022, 2025). "Chemotherapy activates tumor-associated macrophages to secrete IL-18, which in turn induces LAT2 expression and LAT2-mediated Gln and Leu uptake in osteosarcoma cells." (PMID 36274066, 2022). "In the TARGET osteosarcoma cohort, IL18 expression was positively correlated with M1 marker CD80 and CD86 and M1 abundance in tumor-infiltrating immune cells." (PMID 36274066, 2022). "Intriguingly, the mRNA expression level of interleukin-18 receptor 1 (IL18R1) was significantly higher in osteosarcoma cell lines than in hFob1.19 normal osteoblast cell line, implying that osteosarcoma cells are more sensitive to IL-18 than normal bone cells." (PMID 36274066, 2022). "The present results of the western blot revealed that the NLRP3 as well as caspase-1, GSDMD, IL-1β, and IL-18 proteins decreased after NLRP3 blockage in osteosarcoma." (PMID 34393801, 2021). "It is worth pointing out that, in osteosarcoma, increased IL-18 expression can be attributed to an increase in tumor resistance derived from the infiltration of suppressor cells of myeloid origin." (PMID 31554368, 2019). "Moreover, the levels of the pro-inflammatory cytokine interleukin 18 are positively correlated with those of myeloid-derived suppressor cells in the peripheral blood of animal models of osteosarcoma." (PMID 40109854, 2025). "The results suggest that blocking IL-18 may reduce the accumulation and function of MDSCs, thereby enhancing the efficacy of anti-PD-1 therapy in osteosarcoma patients." (PMID 40115022, 2025). "In addition, the expression of LAT2 was positively correlated with expression of IL-18 as well as the expression of CD47 in osteosarcoma specimens before and after chemotherapy." (PMID 36274066, 2022). "In addition, we observed positive correlations between CD47 and IL-18 in three different GEO cohorts of osteosarcoma patients." (PMID 36274066, 2022). "In the K7M2 osteosarcoma model, IL-18 seems to be implicated in MDSC recruitment at the tumor site and the association of anti-PD-1 with IL-18BP (an inhibitor of IL-18) increases the proportion of CD8+ IFNγ+ GzmB+ T cell tumor infiltration, and decreases tumor weight." (PMID 33261061, 2020). "Inhibition of IL-18-mediated MDSC accumulation improves the efficacy of ICIs, such as anti-PD-1 drugs, in treating osteosarcoma." (PMID 40109854, 2025). "Combining anti-IL-18 with anti-PD1 therapy effectively reduced levels of G-MDSC and M-MDSC, enhancing T cell infiltration and immune function, providing a new strategy for osteosarcoma immunotherapy." (PMID 38915446, 2024). "In addition, the expression of IL-18 and CD47 in osteosarcoma specimens before and after chemotherapy was correlated, and the changes of CD47 expression caused by chemotherapy were also correlated with the changes of IL-18 induced by chemotherapy." (PMID 36274066, 2022). "IHC staining of paired pre- and post-chemotherapy specimens from osteosarcoma patients revealed significant increase of IL-18 after chemotherapy without obvious change in total macrophage numbers." (PMID 36274066, 2022).
peritonitis (8 papers, 2018 to 2025). Inflammation of the peritoneum (tissue that lines the abdominal wall and covers most of the organs in the abdomen). "Previous reports demonstrated that IL-18 promoted IL-17A secretion in a cecal slurry-induced peritonitis model and, along with IL-23, induced T cells to produce IL-17A in an experimental autoimmune encephalomyelitis model." (PMID 40777291, 2025). "The intraperitoneal injection of MSU leads to NLRP3 inflammasome-dependent peritonitis, which is characterized by IL-1β and IL-18 production and the neutrophil influx into the peritoneal cavity." (PMID 36975504, 2023). "In the present study, using a murine model of LPS-induced acute peritonitis, we demonstrated administration of IL-10 inhibits inflammatory response via reduction of proinflammatory cytokines, including IL-1β, IL-18, and TNF-α in PLF and serum." (PMID 33414479, 2021). "Similar to the in vitro effects, Crocin attenuated the secretion of IL-1β and IL-18 and neutrophil recruitment in an MSU-induced mouse peritonitis model." (PMID 36975504, 2023). "Although we have not assayed changes in IL-18 during peritonitis, our analysis of IL-1β production suggests the rapid activation of the NLRP3 inflammasome system following SES challenge." (PMID 37272871, 2023).